ROCK1 (Rho associated coiled-coil containing protein kinase 1)
Diseases named in the same sentence as ROCK1 in open-access papers (continued):
Sharing a sentence is not in itself a finding about the gene and the disease.
cancer (continued). "In the field of cancer research, ROCK1 has been reported to be cleaved into activated ROCK1, which has a molecular weight of 130 kDa, through the proteolytic cleavage of its C-terminal autoinhibitory domain eventually leading to apoptosis." (PMID 31578315, 2019). "The fraction of cancers with strong ROCK1 positivity increased from 13.4% in patients aged below 50 years to 20.5% in elderly patients (>70 years, p<0.0001)." (PMID 31557128, 2019). "In cancer, ROCK1 staining was considered weak, moderate, and strong in 22%, 53%, and 18% of cases respectively." (PMID 31557128, 2019). "To estimate the impact of AR on ROCK1 expression, we used AR expression data from a previous study, Data on both ROCK1 and AR were available from 6994 cancers." (PMID 31557128, 2019). "Rho-associated kinases, known as two isoforms, ROCK1 and ROCK2, have been shown to induce stress fiber formation, cancer cell migration and metastasis." (PMID 31197105, 2019). "In cancers, at least weak ROCK1 staining was found in 92% of the cases, and was considered weak in 22%, moderate in 53%, and strong in 18% of tumors." (PMID 31557128, 2019). "In recent years, high expression of ROCK1 has been reported in several human cancers and often correlated with poor survival." (PMID 31263414, 2019). "The average Ki67-LI increased from 1.62±0.12 in cancers lacking ROCK1 expression to 2.28±0.07 (weak), 2.93±0.05 (moderate) and to 3.72±0.08 in cancers with strong ROCK1 expression." (PMID 31557128, 2019). "To test if RBP4 induced cancer cell migration is RhoA/Rock1 dependent, we added Y-27632 to our RBP4 overexpression cells." (PMID 29642915, 2018). "Increased ROCK1 expression has been observed in a number of pathological conditions, including cancer." (PMID 28841710, 2017). "Increased expression of ROCK1 is reported in several human cancers and correlated with poor survival." (PMID 28978024, 2017). "ROCK1 enhances cancer cell motility and invasiveness by modulating reorganization of the actin cytoskeleton." (PMID 28978024, 2017). "RhoA/ROCK1 signaling has been shown to play an important role in cancer development and progression." (PMID 28841710, 2017). "Other target genes, including Rho-associated, coiled-coil containing protein kinase 1 (ROCK1) and tripartite motif containing 2 (TRIM2), have also been identified as being controlled by miR-145 in cancer." (PMID 27412561, 2016). "Recent studies showed that ROCK1 functions as an oncogene and possesses a wide range of functions in cancers, such as cell motility, apoptosis, survival, proliferation and metastasis." (PMID 27557508, 2016). "Rho-associated kinase and its isoforms (ROCK-1 and ROCK-2) promote cancer invasion and migration by regulating actin rearrangements in the cytoskeleton." (PMID 27102150, 2016). "Activating mutations in Rho GTPases have recently been described in human cancers as well as in some of their effectors such as the kinase ROCK1." (PMID 25677806, 2015). "RhoB, RhoC and ROCK-1 mRNA levels were significantly higher in ccRCC tissues compared with non-cancer tissues." (PMID 21119662, 2011). "Notably, the relationship between CEP55 and RhoA/ROCK1 signaling has been discovered, with a focus on therapeutic consequences in cancer." (PMID 39023191, 2024). "As a result, there could be positive health benefits that would contribute to positive selection for ROCK1 to be caspase cleaved to enable cell death to be less necrotic-like and inflammatory, which consequently might actually lead to worse cancer outcomes." (PMID 38616733, 2024). "Neither DJ-Allyl (18.1%), DJE4 (13.4%), nor DJ-Morpholine (8%) induced significant apoptotic cell death, further suggesting that targeting ROCK1/2 selectively inhibits cancer cell migration whereas multi-kinase inhibition of ROCK1/2 and MRCK α/β leads to cell death." (PMID 37630974, 2023). "ROCK1 was reported to be involved in the progression of several cancers, including ESCC." (PMID 36781836, 2023).
cancer (continued). "Several studies have found the important role of ROCK1 in cancers." (PMID 37683138, 2023). "EIF4A1 has been reported to directly determine the selective translation of oncoproteins, such as myc, myb, notch, cdk6, bcl-2 and ROCK1, which are critical regulators contributing to cancer survival, proliferation, migration, invasion, metastasis and chemoresistance." (PMID 36101357, 2022). "The interactions between PFN1 and ROCK1 may be much more complex in vivo and play important roles in cancer progression, which needs further investigation in the future." (PMID 35586060, 2022). "Indeed, we recently contributed to work identifying that PKN2 and ROCK1 collaborate to mediate rear end retraction in durotaxis, focusing on mesenchymal migratory cancer cell models, a process which also requires mechanical activation of YAP." (PMID 35081338, 2022). "For instance, ROCK1 was found to be a target of miR-143/145 in smooth muscle cells, miR-124, miR-135a, miR-145, miR146a, miR-148a, miR-186, miR-340, miR-584, and miR-1280 in cancer cells." (PMID 35043239, 2022). "The mechanisms involved in the influence of miR-335-5p on cancers may be related to regulation of downstream signaling, such as ROCK1 and mitogen-activated protein kinase (MAPK), which was not clarified in this study." (PMID 33816305, 2021). "Western blotting, kinase functional/cellular activity, and computational assays indicated DJ4 selectively acts as an ATP competitive inhibitor of the kinases ROCK1/2 and MRCKα/β, which are responsible for the processes needed for cancer cell migration/invasion." (PMID 34638385, 2021). "ROCK1 is a famous oncogene and its role has been identified in assorted human cancers." (PMID 34536977, 2021). "Cancer cell invasion and proliferation are crucial to cancer progression; we therefore examined whether ROCK1 also regulated A549 cell proliferation and mobilization." (PMID 32554853, 2020). "ROCK1 is involved in cancer progression and its inhibition occurs during cancer metastasis." (PMID 32163546, 2020). "Furthermore, several somatic mutations in genes encoding ROCK-1 or ROCK-2, leading to a gain-of-function, have been identified in several cancers and especially in colorectal cancer." (PMID 32770034, 2020). "LncRNA CCHE1 siRNA silencing led to inhibited ROCK1 expression in cancer cells." (PMID 32660450, 2020). "Indeed, the hyperactive ROCK1 signaling pathway was reported to promote migration and invasion of many types of cancer cells." (PMID 33168781, 2020). "Whether ROCK1 promotes cancer cell viability by inhibiting LATS2 and subsequently blocking Bax- or JNK-induced mitochondrial apoptosis in NSCLC remains to be determined." (PMID 32554853, 2020). "In cancer biology, ROCK1 promotes cancer development and progression by mediating tumor metastasis." (PMID 32660450, 2020). "In addition, ROCK1 overexpression attenuated the inhibitory effects of lncRNA CCHE1 on cancer cell migration and invasion (p < 0.05)." (PMID 32660450, 2020). "Furthermore, ROCK1 has been developed as a potential therapeutic target for diseases like neurological disorders, cardiovascular diseases, and cancers." (PMID 31263414, 2019). "Increased expression of Rho GTPases and ROCK1 were often observed in cancers." (PMID 31443665, 2019). "The specific function of ROCK-1 in cancer cells remains controversial." (PMID 31750234, 2019). "Previous studies have shown that increased CDC42 and ROCK1 expression directly correlates with elevated actomyosin contractility, actin turnover and actin polymerization and eventually facilitate the migration of cancer cells." (PMID 31664083, 2019). "ROCK1 was also broadly reported as a proliferation- and metastasis-related gene in various cancers." (PMID 29753317, 2018). "Rho-associated kinases 1 and 2 (ROCK1/2) are Rho-GTPase effectors that control key aspects of the actin cytoskeleton, but their role in proliferation and cancer initiation or progression is not known." (PMID 26765561, 2016).
cancer (continued). "RhoA/ROCK1 is known as a downstream pathway of RhoGDIα in many cancers." (PMID 27557508, 2016). "In this respect, the reduction of miR-135a expression in cancers may result in uncontrolled ROCK1 expression that may become excessive and thereby inhibit cell invasion." (PMID 27227989, 2016). "Next, we examined subcellular localization of CXADR, which was recently reported to be required for adherens and tight junction formation during porcine blastocyst development (Kwon, Kim & Choi, 2016) and shown to directly associated with ROCK1 and ROCK2 in human carcinoma cells." (PMID 27077008, 2016). "ROCK1 is an important player in regulating the motility and migration of cancer cells." (PMID 25148701, 2014). "Conversely, ROCK1 has been largely reported as a marker of worse prognosis in many cancer types." (PMID 25380619, 2014). "The use of ROCK1 as a potential target in cancer therapy has been suggested previously." (PMID 25538140, 2014). "The development of drugs regulating the expression of Rac1, Rock1 and Pak1 may more accurately regulate actin activity which may be more beneficial in the prevention and treatment of diseases such as cancer." (PMID 23298303, 2014). "This is the first report to demonstrate that ROCK1 correlates with a good prognosis in cancer." (PMID 25380619, 2014). "The Rho associated coiled-coil containing protein kinase (ROCK1 and ROCK2) and myotonic dystrophy-related Cdc-42 binding kinases (MRCKα and MRCKβ) are critical regulators of cell proliferation and cell plasticity, a process intimately involved in cancer cell migration and invasion." (PMID 37630974, 2023). "Similarly, cancer-related miRNAs can bind to 3′ UTR of ROCK1 to regulate its expression." (PMID 36177350, 2022). "The present results indicate that arnidiol efficiently induced apoptosis in human cancer cells by triggering mitochondrial fission and that this process was due primarily to the interaction and recruitment of Drp1 and cofilin to mitochondria via the activation of ROCK1 signaling." (PMID 32075676, 2020). "ROCK1 is the key mediator of RhoA activity, and is a multifunctional member of the AGC (protein kinase A/G/C) kinase family that has also been implicated in the modulation of stress fiber assembly, cell contraction, apoptosis, migration, and invasion of multiple cancer cell types." (PMID 28841710, 2017). "However, reports of ROCK1 in cancer stem cells are very rare." (PMID 27557508, 2016). "Moreover, elevated ROCK1 levels in the invasive front was an independent protective factor (HR =0.22 for moderate expression, and HR =0.33 for strong expression) with regard to cancer-specific survival (p =0.0054)." (PMID 25380619, 2014). "Tsai and co-workers revealed that miR-148a directly inhibits ROCK1 and c-Met, leading to the downregulation of HIF-1α, a key factor in hypoxia-induced cancer progression." (PMID 40871106, 2025). "ROCK1, located in 18q11.1, is a member of the serine/threonine kinases family, and CDCP1 was previously suggested to possibly play a role in promoting cancer metastasis." (PMID 40556338, 2025). "Many operations, that is, activation of GPER and reduction of ROCK1, TAGLN2, and FCHO2 expressions, are involved in the prevention of cancer development." (PMID 40078339, 2025). "Activation of GPER and reduction in the expressions of ROCK1, TAGLN2, and FCHO2 are some of the processes modulated by punicalagin that inhibit the development of cancer." (PMID 40018013, 2025). "The results showed that GluOC inhibited the apoptosis of cancer cells via the ROCK1/JAK2/PIK3CA/AKT signalling pathway, promoted cell cycle progression, reduced ROS levels during cancer cell death, and promoted an increase in stem cell properties." (PMID 39054484, 2024).
cancer (continued). "In this scenario, from our in-depth analysis, we found that miR-584-5p modulates the expression of important target genes such as MMP-14, ROCK1 and YAP1, influencing multiple cancer mechanisms, including drug resistance, motility, angiogenesis and cell death." (PMID 39000555, 2024). "In our study, GluOC activated the ROCK1/MYPT1/MLC2 signalling pathway by promoting the expression of ROCK1, thereby stimulating the migration of cancer cells." (PMID 39054484, 2024). "Activation of TRPV4 remodels the cytoskeleton by regulating ROCK1 and promotes sc polarity via AMPK/MLC/ERM axis, thereby affecting the migration, invasion and adhesion to blood vessel of metastatic cancer cells." (PMID 37369706, 2023). "In particular, RhoBTB1 was reported to co-immunoprecipitate with ROCK1 in COS7 cells and to inhibit cancer cell invasion by an unclear mechanism." (PMID 35358093, 2022). "It is worth noting that some miRNAs target both ROCK1 and ROCK2, such as miR-124 and miR135a in cancer cells." (PMID 35043239, 2022). "Elevated protein expression of ROCK1 and ALK has a strong prognostic value for cancers in humans as well as EMN in equines." (PMID 34199079, 2021). "Previously, it had been shown that inhibition of ROCK1 and ROCK2, in addition to MRCKα and MRCKβ strongly impaired migration of cancer cells." (PMID 33921698, 2021). "In SCLC cells, MCM3AP-AS1 overexpression increased ROCK1 and promoted cancer cell invasion and migration, while miR-148a overexpression showed the opposite effects and attenuated the effects of MCM3AP-AS1 overexpression on ROCK1 expression and cell behaviors." (PMID 34271873, 2021). "We show that both the pharmacological and molecular inhibition of ROCK-1 and ROCK-2 induce SW620 cancer cell invasiveness, by promoting the activity of the pro-invasive voltage-gated sodium channel NaV1.5 activity." (PMID 32770034, 2020). "Some target genes of miR-124 have been described, such as ROCK1, SNAIL2, CDK4, CAV1, and ERK2, whose action can suppress cancer growth and metastasis." (PMID 31052530, 2019). "Strong ROCK1 staining was found in 3% of AR-negative, but in 27% of strongly AR positive cancers, in 13% of ERG-negative but in 25% of ERG positive cancers, and in 12% of PTEN normal but in 26% of PTEN deleted cancers." (PMID 31557128, 2019). "The target genes of miR-184a identified in cancer are USP4, ROCK1, ERBB3, BCL-2, WNT10B, and CDC25B." (PMID 31052530, 2019). "Previous studies have shown that miR-124 inhibits cancer cell invasion and metastasis by targeting other molecules, including slug, Rac-1, SMYD3, SphK1, and ROCK1." (PMID 28270130, 2017). "Some novel isoform selective inhibitors are becoming commercially available and will serve as valuable tools for further dissecting the roles of ROCK1 and ROCK2 in cancer and other diseases." (PMID 26725045, 2016). "In particular, two proteins called ROCK1 and ROCK2 are known to be important for helping cancer cells move." (PMID 26765561, 2016). "Numerous miRNAs involved in regulating ROCK1 and ROCK2 expression and activity have been identified in cancer tissues." (PMID 26725045, 2016). "Recent studies have validated some of the mutations and gene variants, with an emphasis on examining those affecting the coding sequence of ROCK1 and ROCK2, and determining their impact on cancer pathogenesis." (PMID 26725045, 2016). "Depletion of the kinases ROCK1 and ROCK2, two known RhoC downstream effectors, similarly decreases cancer interaction with ECs." (PMID 25677806, 2015). "Along with the related ROCK1 and ROCK2 kinases, the MRCK proteins initiate signalling events that lead to contractile force generation which powers cancer cell motility and invasion." (PMID 25288205, 2014). "We selected potential miR-148a cancer-related target genes, namely ITGA11, ITGB8, VAV2, ROCK1 and WASL, which are known to be involved in integrin pathway-promoting cell migration, motility, actin polymerization, and cytoskeleton remodeling." (PMID 25277193, 2014).
cancer (continued). "In contrast our FRET studies identified a direct interaction between ROCK1 and LIMK2 in concentrated foci in the cytoplasm of cancer cells with a mesenchymal morphology." (PMID 18852895, 2008). "We then perform immune infiltration by TIMER and ESTIMATE in pan-cancer and the result showed a negative correlation between DCs and ROCK1 in SARC, which was consistent with xCell immune infiltration analysis in PMOP." (PMID 37683138, 2023). "Therefore, we aimed to further investigate the role of ROCK1, the hub gene identified in PMOP, in the context of pan-cancer, with the potential to facilitate early detection and precise therapeutic intervention for various types of cancer." (PMID 37683138, 2023). "ROCK1/2 inhibitors such as fasudil, AT13148, Y-27632, YM529/ONO-5920, PT-262, WF-536 and RKI-1447 have shown significant cancer inhibition." (PMID 36781836, 2023). "Despite accumulating evidence indicating that ROCK1 and PYROXD1 play vital roles in the metastasis of various cancers, the crosstalk between ROCK1 and PYROXD1 in LSCC is unknown." (PMID 36334145, 2022). "It was reported that ROCK1 and NFE2L1 could activate the activity of Wnt signaling pathway in human cancers." (PMID 34536977, 2021). "ROCK1 and ROCK2 are central regulators of actin-myosin contractility and actin cytoskeleton dynamics and are being discussed as potential therapy targets in cancer and other diseases." (PMID 33777943, 2021). "That ROCK1 expression lacked prognostic impact in cancers defined by a comparable classical or quantitative Gleason grade demonstrates how difficult it is for a molecular marker to compete with classical histomorphological features." (PMID 31557128, 2019). "While the mechanism of activation of CDC42/RAC1 by RHOG, the MAPK by RAC1, as well as the intersection with the RHOA/ROCK1/2 pathways remain topics for future work, we believe this study sheds the light on RHOG as a potentially promising target for anti-angiogenesis in cancer therapeutics." (PMID 30781697, 2019). "For example, strong ROCK1 expression was found in 27.2% of pT3b-pT4 tumors and 30% of nodal-positive cancers, but only in 15% of pT2 cancers and 20% of nodal-negative cancers (p<0.0001 each)." (PMID 31557128, 2019). "There was a strong positive association between AR expression and ROCK1 expression in all cancers as well as in subsets of ERG negative and ERG positive cancers." (PMID 31557128, 2019). "Recently developed ROCK1 and ROCK2 isoform-specific genetically modified mouse models have offered a unique opportunity to analyze in vivo physiological and pathological functions of ROCK1 and ROCK2, including cancer development and progression." (PMID 26725045, 2016). "In addition to those miRNAs interacting with ROCK1, there are also miRNAs interacting with ROCK2 in cancers, for instance, miR-139, miR-124 and miR-101 in hepatocellular carcinoma, miR-200b/c in cholangiocarcinoma, and miR-138 in oral cancer." (PMID 26725045, 2016). "Besides, ROCK1 targeted by hsa-miR-4689 and PLCB1 targeted by hsa-miR-3911 were significantly involved in Proteoglycans in cancer, and PLCB1 was Rap1 signaling pathway and Glutamatergic synapse (FDR = 0.022324586)." (PMID 26879603, 2016). "However, regulation of expression of ROCK1 and ROCK2 is often abrogated in several diseases, including several cancers." (PMID 27203208, 2016). "Our data suggest that ROCK1 and ROCK2 might act downstream of RhoC to regulate cancer cell adhesion to and transmigration across ECs." (PMID 25677806, 2015). "ROCK1 and ROCK2 depletion also induced a delay of cancer cell intercalation within EC monolayers." (PMID 25677806, 2015). "Interestingly, no cancer cells that lack both ROCK1 and ROCK2 have been found, indicating that ROCK proteins are essential for tumorigenesis." (PMID 35379935, 2022). "Additionally, G-Rh1 suppressed the mRNA expression of RhoA, ROCK1, MMP1, and MMP9 in cancer cell." (PMID 36500403, 2022).